ENSG00000273537
Gene: Miscellaneous RNA gene on chromosome 2 (144,520,456 to 144,520,555, forward strand). Ensembl gene ENSG00000273537.
Gene Ontology:
Biological process: positive regulation of gene expression